PSEN2 (presenilin 2)
Diseases named in the same sentence as PSEN2 in open-access papers (continued):
Sharing a sentence is not in itself a finding about the gene and the disease.
Alzheimer disease (continued). "These are two brain-specific uncoupling proteins (SCL25A27 and SLC25A14) and three genes linked to Alzheimer Disease (PSEN1, PSEN2, and BACE1)." (PMID 40901366, 2025). "PSEN1, PSEN2, and APP mutations cause Alzheimer’s disease (AD) with an early age at onset (AAO) and progressive cognitive decline." (PMID 39754192, 2025). "While most Alzheimer’s disease cases are sporadic, FAD mutations in PSEN1, PSEN2, and APP are nearly completely penetrant." (PMID 39754192, 2025). "Another frameshift variant in this position (c.1073-2delA; p.G359Lfs*74) was also reported in two patients with mild cognitive impairment and Alzheimer’s disease, in which expression studies showed reduced PSEN2." (PMID 39200345, 2024). "In a study of German early-onset Alzheimer’s disease (EOAD) patients employing whole-exome sequencing, variants linked to presenilin 2 (PSEN2) were identified." (PMID 38339035, 2024). "Familial Alzheimer’s disease typically appears earlier in life and is caused by hereditary genetic mutations in amyloid precursor protein (APP), presenilin 1 (PSEN1), and presenilin 2 (PSEN2)." (PMID 38410184, 2024). "Autosomal dominant Alzheimer's disease (ADAD) is a rare form of Alzheimer's disease (AD) that arises from mutations in the genes encoding presenilin 1 (PSEN1), presenilin 2 (PSEN2), or amyloid precursor protein (APP), all affecting APP processing." (PMID 38666355, 2024). "Changes in three distinct genes—amyloid precursor protein (APP), amyloid beta (A4), presenilin 1 (PSEN1), and presenilin 2 (PSEN2)—have been pinpointed as the primary culprits behind early-onset Alzheimer’s disease (EOAD)." (PMID 38785945, 2024). "Familial Alzheimer’s disease (fAD) is a rare, inherited form of AD often linked to mutations in the APP and presenilin 1 (PSEN1) and presenilin 2 (PSEN2) genes." (PMID 39684324, 2024). "Presenilin-2 (PSEN2 on chromosome 1) is a homologous gene of presenilin-1 (PSEN1 on chromosome 14), which is a causative factor in autosomal dominant early-onset Alzheimer’s disease (EOAD)." (PMID 39273625, 2024). "The presenilin 2 gene (PSEN2, MIM 600759) encodes a transmembrane key protein implicated in Alzheimer’s disease (AD), particularly in the inherited forms of the disease." (PMID 39337275, 2024). "Molecular and genetic studies in AD patients have identified three primary genetic mutations associated with Early-Onset Alzheimer’s Disease (EOAD), linked with genes encoding amyloid precursor protein (APP), presenilin 1 (PSEN1), and presenilin 2 (PSEN2)." (PMID 39000011, 2024). "In contrast to late-onset Alzheimer’s disease, early-onset Alzheimer’s disease (EOAD) is often caused by autosomal-dominant mutations, specifically in APP, PSEN1, and PSEN2." (PMID 37341843, 2023). "The etiology of early-onset Alzheimer’s disease (EOAD) is associated with alterations in the production of amyloid beta (Aβ) species caused by mutations in the APP, PSEN1, and PSEN2 genes." (PMID 37108607, 2023). "A small proportion of patients with Alzheimer’s disease (AD) carry autosomal-dominant mutations in the APP, PSEN1, or PSEN2 genes (adAD)." (PMID 37131241, 2023). "Mutations in the presenilin-1 (PSEN1), presenilin-2 (PSEN2), and amyloid precursor protein (APP) genes have been commonly identified in early-onset Alzheimer's disease (EOAD)." (PMID 37051054, 2023). "Regarding Presenilin-2, it is part of the complex that catalyzes the cleavage of APP and mutations in PSEN2 are causative of dominantly inherited Alzheimer’s disease." (PMID 37784196, 2023). "Although most cases of Alzheimer’s disease have a sporadic onset, familial Alzheimer’s disease is mainly caused by mutations in three genes: APP, presenilin 1 (PSEN1), and presenilin 2 (PSEN2)." (PMID 36672267, 2023). "In this study, we systematically explored the relationship between Alzheimer's disease (AD) and non‐pathogenic variants of APP, PSEN1, and PSEN2 in a total of 3557 individuals in a Chinese population." (PMID 36217304, 2023).
Alzheimer disease (continued). "The emerging world faces a genetic risk of Alzheimer’s disease (AD) due to mutations in PSEN1 (located on chromosome 14), PSEN2 (located on chromosome 1), and APP (located on chromosome 21), which are known to cause familial Alzheimer’s disease (FAD)." (PMID 38173557, 2023). "Four genes have been identified to be associated with Alzheimer’s disease, namely, the amyloid precursor protein (APP) gene, the presenilin 1 (PSEN1) gene, the presenilin 2 (PSEN2) gene and the apolipoprotein E (ApoE) gene." (PMID 37362440, 2023). "Presenilin 2 (Psen2), which cleaves proteins such as APP (amyloid-beta precursor protein) and has been shown to cause Alzheimer’s disease, displays a change in ASE (Fisher’s exact; q = 0.00001) and a 2.7-fold decrease in RNA transcript levels." (PMID 35485945, 2022). "Familial Alzheimer's disease (FAD) is caused by dominantly inherited mutations in APP, PSEN1 and PSEN2." (PMID 34319632, 2022). "Familial Alzheimer's disease (FAD) is caused by autosomal dominant mutations in the PSEN1, PSEN2 or APP genes, giving rise to considerable clinical and pathological heterogeneity in FAD." (PMID 34319632, 2022). "Autosomal dominant Alzheimer’s disease (ADAD) accounts for approximately 1% of all Alzheimer’s disease (AD) cases and is usually caused by mutations in one of three known genes, namely PSEN1 (OMIM 104311), APP (OMIM 104760), and PSEN2 (OMIM 1600759)." (PMID 36380395, 2022). "Monogenic forms of Alzheimer’s disease (AD) have been identified through mutations in genes such as APP, PSEN1, and PSEN2, whilst other genetic markers such as the APOE ε carrier allele status have been shown to increase the likelihood of having the disease." (PMID 36175824, 2022). "Along with mutations in PSEN1 and PSEN2, APP is one of the most studied genes known to cause Alzheimer’s disease." (PMID 36175824, 2022). "Mutations in genes encoding presenilin 1 or 2 (PSEN1 or PSEN2) and amyloid precursor protein (APP) have been linked to early-onset Alzheimer’s disease." (PMID 36077172, 2022). "For autosomal dominant early-onset Alzheimer's disease (EOAD), mutations in the APP, presenilin 1 (PSEN1), or presenilin 2 (PSEN2) gene sequence are a major risk factor, while the APOE4 allele is a major risk factor for late-onset Alzheimer's disease (LOAD)." (PMID 34122554, 2021). "Forty-five items were chosen and analyzed.PSEN1 mutations are the commonest cause of geneticearly-onset Alzheimer’s disease (EOAD), followed by PSEN2 andAPP mutations." (PMID 32973976, 2020). "Well over 200 mutations causing familial Alzheimer’s disease have been identified in the human PSEN1 and PSEN2 genes." (PMID 32658922, 2020). "Alzheimer’s disease is caused by a mutation in the APP gene, or in the presenilin 1 (PSEN1) and 2 (PSEN2) genes." (PMID 29879811, 2019). "Presenilin 1 (PSEN1), presenilin 2 (PSEN2), and amyloid precursor protein (APP) mutations are responsible for autosomal dominant early-onset Alzheimer’s disease (AD-EOAD)." (PMID 31440394, 2019). "Familial Alzheimer's disease (FAD): a form of Alzheimer's disease caused by mutations in a specific set of genes (APP, PSEN1 and PSEN2) that are passed down from parents to offspring in an autosomal-dominant manner." (PMID 29784664, 2018). "Mutations in the Amyloid Precursor protein (APP), Presenilin 1 (PSEN1) and Presenilin 2 (PSEN2) genes and duplications of the APP locus are the main causes of autosomal dominant early-onset Alzheimer's disease." (PMID 29875629, 2018). "Familial Alzheimer’s disease (FAD), due to dominantly inherited mutations in the presenilin 1 (PSEN1), PSEN2, and amyloid precursor protein (APP) genes, accounts for a small proportion (approximately 1%) of all cases of AD." (PMID 29562504, 2018). "In a cohort including patients with familial Alzheimer disease as well as sporadic cases of early-onset Alzheimer disease, Dominique Campion and colleagues identify previously unreported mutations to PSEN1 and PSEN2." (PMID 28350801, 2017).
Alzheimer disease (continued). "For example, in Alzheimer's disease, we noted that all associated genes (APP, PSEN1, and PSEN2) were reported to show an increase in Aβ in neurons (Fig EV3A)." (PMID 29051230, 2017). "Mutations in the amyloid protein precursor (APP), presenilin-1 (PSEN1), and presenilin-2 (PSEN2) genes are a known cause of familial, early-onset Alzheimer disease (EOAD) (onset below age 65)." (PMID 28350801, 2017). "Mutations in APP, APOE, PSEN1, PSEN2 and MAPT genes were found to cause Alzheimer’s disease pathogenesis." (PMID 26784894, 2016). "In familial forms of Alzheimer’s disease, mutations in Amyloid precursor protein (APP), Persenilin-1 (PSEN1), and Presenilin-2 (PSEN2) genes lead to excessive formation of neurotoxic peptide amyloid- β (Aβ) plaques which aggregate extracellularly." (PMID 25690002, 2015). "Familial Alzheimer’s disease (AD), mostly associated with early onset, is caused by mutations in three genes (APP, PSEN1, and PSEN2) involved in the production of the amyloid β peptide." (PMID 25914626, 2015). "The discovery of monogenic forms of Alzheimer's Disease (AD) associated with mutations within PSEN1, PSEN2, and APP genes is giving a big contribution in the understanding of the underpinning mechanisms of this complex disorder." (PMID 24377094, 2013). "Less than 2% of AD cases are early-onset Alzheimer's disease (EOAD), which onsets prior to age 60 with genetic mutations in APP, presenilin 1, or presenilin 2 genes." (PMID 24367332, 2013). "Mutations in PSEN1 and PSEN2 genes, which encode polytopic proteins termed presenilin 1 (PS1) and presenilin 2 (PS2), respectively, cause autosomal dominant early-onset familial Alzheimer's disease (FAD)." (PMID 20798900, 2010). "Familial Alzheimer's disease-linked variants of presenilin (PSEN1 and PSEN2) contribute to the pathophysiology of disease by both gain-of-function and loss-of-function mechanisms." (PMID 18834536, 2008). "In 2009, no pathogenic variants were identified in the APP, PSEN1, and PSEN2 genes in the three living patients with Alzheimer's disease, and these negative findings were also confirmed in ES." (PMID 39810256, 2025). "Interestingly, several upregulated DE genes were related to neurodegenerative diseases, such as genes related to Alzheimer’s disease: PSEN2, TREM2, and GAB2; Parkinson’s disease: ATP13A2 and DCTN1; and amyotrophic lateral sclerosis: TAF15 and FUS." (PMID 40877796, 2025). "In order to perform an accurate systematic review on the relationship between Alzheimer’s disease and presenilin 2, we selected studies with high statistical value, such as meta-analyses, multicenter studies with large samples, systematic reviews, and clinical trials." (PMID 39200345, 2024). "Additionally, mutations in the amyloid precursor protein (APP), presenilin 1 (PSEN1), and presenilin 2 (PSEN2) genes have been identified in patients with an autosomal-dominant form of early-onset Alzheimer’s disease." (PMID 38926887, 2024). "Although Alzheimer’s disease arises predominantly as a sporadic condition of late adult life, there are rarer early-onset Mendelian forms caused by mutations in the APP gene or in genes (PSEN1 and PSEN2) known to alter its enzymatic cleavage." (PMID 38287166, 2024). "Familial Alzheimer's disease is characterized by a strong genetic component and is typically associated with mutations in specific genes, including those coding for amyloid precursor protein (APP), presenilin 1 (PSEN1), and presenilin 2 (PSEN2)." (PMID 38169888, 2024). "In addition, some Boolean operators such as “AND” and/or “OR” were also applied to manage the search: [(“Alzheimer ́s disease” OR “AD”) AND (“Presenilin 2” OR “PSEN 2”)]." (PMID 39200345, 2024). "Familial Alzheimer’s disease (FAD) is known to be associated with mutations in the APP, PSEN1, and PSEN2 genes involved in Aβ production; however, these genetic defects occur in only about 10–20% of FAD cases, and more genes and new mechanism causing FAD remain largely obscure." (PMID 37365538, 2023).
Alzheimer disease (continued). "In this study we compared cases of EOAD (without known causal mutations in APP, PSEN1 or PSEN2), Alzheimer’s disease in individuals who had DS (AD-DS), and healthy ageing disomic individuals." (PMID 37580797, 2023). "Since obesity is closely related to T2DM, and Alzheimer’s disease (AD) is also recognized as “type III diabetes,” we checked the expression of genes encoding proteins that are involved in amyloid-beta (Aβ) generation (ADAM10, BACE1, PSEN2, and GSK3β)." (PMID 37432552, 2023). "However, only 5–10% of patients with early-onset Alzheimer’s disease are carrying a pathogenic mutation in APP, PSEN1, PSEN2, or the common apolipoprotein E (APOE) ɛ4 allele." (PMID 36077172, 2022). "As the infection progresses, we noted an enrichment for genes associated with neurodegenerative disorders (e.g., Amyotrophic lateral sclerosis, Huntington disease, Parkinson disease, and Alzheimer’s disease) such as Apoe, Trem2, and Psen2 (Fig. 3Hleft, Supplementary Datas 9 and 10)." (PMID 36180478, 2022). "This work is an extension of current research, in which we present new changes in the genes related to Alzheimer’s disease, such as the amyloid protein precursor, β-secretase, presenilin 1, and presenilin 2, in the circulating lymphocytes of neonates with perinatal asphyxia treated with hypothermia." (PMID 35743334, 2022). "In a small percentage of patients, Alzheimer’s disease (AD) is characterized by an early onset due to a mutation in one of three identified genes: amyloid-beta precursor protein (AβPP), Presenilin 1 (PSEN1), and Presenilin 2 (PSEN2)." (PMID 32581318, 2021). "In fact, it has been shown that sorcin interacts with presenilin 2, a component of the γ-secretase, which is involved in the generation of 39–42 amino acid amyloid-β peptides (Aβ) from cleavage of the Aβ protein precursor in Alzheimer’s disease (AD)." (PMID 34205207, 2021). "Moreover we report the prevalent role of APP-Aβ degradation genes upon genes involved in APP-Aβ production as well as Mendelian genes causative for Alzheimer’s disease (APP, PSEN1 and PSEN2)." (PMID 32345996, 2020). "In addition, three gene mutations are responsible for Alzheimer’s disease, including presenilin 1 (PSEN1), presenilin 2 (PSEN2) and amyloid precursor protein (APP), with presenilin 1 being the most common." (PMID 32085610, 2020). "Although approximately 90% of Alzheimer’s disease cases occur sporadically, mutated genes coding for either amyloid precursor protein (chromosome 21) or presenilin-1 (PS1; chromosome 14) or presenilin-2 (PS2; chromosome 1) are found in early-onset familial forms of AD." (PMID 32079163, 2020). "Additionally, we detected 4 P-SMRs involved in Alzheimer’s disease (Psen2), Parkinson’s disease (Dnajc6) and major depression disorder (Htr2a and Htr5a)." (PMID 32992647, 2020). "Autosomal dominant (familial) Alzheimer's disease, due to mutations in presenilin 1 (PSEN1), presenilin 2 (PSEN2), or amyloid precursor protein (APP) genes, shares many features, both pathophysiologically and clinically, with the much more common sporadic form of the disease." (PMID 29413314, 2018). "Surprisingly, targeted exome sequencing of large multiplex pedigrees with LOAD identified mutations in APP, PSEN1, and PSEN2,11, 12 indicating that rare coding sequence variants even in genes associated with early onset Alzheimer disease (AD) may account for a portion of disease risk in LOAD." (PMID 26101835, 2015). "Alzheimer's disease (AD) is a complex disorder with some cases known to be caused by mutations in 3 genes: the amyloid precursor protein (APP), Presenilin 1 (PSEN1), and Presenilin 2 (PSEN2)." (PMID 24958194, 2014). "Also the relative contribution of PSEN1, PSEN2, and APP mutations to early onset Alzheimer's Disease (EOAD) is the subject of considerable controversy, and mutation frequency is highly dependent upon the studied population." (PMID 24377094, 2013).
Alzheimer disease (continued). "This study was conducted to evaluate the efficacy of the herbal formula PM012 on an Alzheimer's disease model, human presenilin 2 mutant transgenic mice (hPS2m), and also to evaluate the toxicity of PM012 in Sprague-Dawely rats after 4 or 26 weeks treatment with repeated oral administration." (PMID 22458507, 2012). "One type of ADRD, early-onset Alzheimer’s disease (EOAD), afflicts about 5% of the population diagnosed with ADRD, while mostly heritable, the known genes associated with this prognosis are amyloid precursor protein (APP), presenilin 1 (PSEN1), and presenilin 2 (PSEN2)." (PMID 38967905, 2025). "While most of the Alzheimer’s disease (AD) cases are sporadic and manifest after age 65 (late-onset AD, LOAD), a subset of patients develop symptoms earlier in life (early-onset, EOAD) due to mutations in the PSEN1, PSEN2, or APP genes with an autosomal-dominant inheritance pattern (AD-EOAD)." (PMID 40869250, 2025). "Major studies into Alzheimer’s disease are focused on unravelling the effects of different forms of β-amyloid, hyperphosphorylated, and/or aggregated tau; on transgenic animals with mutations in APP, PSEN1, PSEN2; or on some genes which increase genetical risk of the disease, such as APOE." (PMID 35203354, 2022). "In contrast, peptides deriving from microtubule-associated protein tau, presenilin 2 and serine/threonine-protein kinase TBK1 were exclusively reported to bind MHC molecules encoded by the HLA-DRB1 1501 allele, a recently-identified susceptibility gene for late onset Alzheimer's disease." (PMID 31824497, 2019). "Less than 1% of Alzheimer's disease cases are familial, with autosomal dominant mutations described in only three genes that lead to early onset disease; APP, presenilin 1 (PSEN1) and presenilin 2 (PSEN2), both of the latter encoding components of the γ-secretase pathway." (PMID 24133413, 2013). "The transmembrane presenilin (PSEN) proteins, PSEN1 and PSEN2, have been proposed to be the catalytic components of the γ-secretase protein complex, which is an intramembranous multimeric protease involved in development, cell regulatory processes, and neurodegeneration in Alzheimer's disease." (PMID 17854491, 2007). "Less than 1% of all AD cases (10% of EOAD) have early onset autosomal dominant Alzheimer disease (ADAD) with a disease-causing variant in amyloid-β precursor protein gene (APP), presenilin 1 (PSEN1) or presenilin 2 (PSEN2)." (PMID 39849058, 2025). "Presenilin-2 is also part of the γ-secretase complex, which plays a critical role in processing APP into amyloid-β peptides, a process central to Alzheimer’s disease (AD) pathology." (PMID 39594648, 2024). "In the CA1 and CA3 regions of the hippocampus and temporal cortex, genes related to Alzheimer’s disease, such as the amyloid protein precursor (APP), β-secretase (BACE1), presenilin 1 (PSEN1) and 2 (PSEN2), are deregulated by ischemia." (PMID 35741821, 2022). "The peptide modulated 77 genes, of which 65 are listed in the AlzBase database and include the hallmarks of Alzheimer’s disease: APP, APOE, PSEN1, and PSEN2." (PMID 28798312, 2017). "Previous studies proved that cis-acting elements were responsible for AS of many genes, e.g., presenilin 2 (PS2) gene, which was abnormally alternatively spliced in a sample related to Alzheimer's disease." (PMID 24575124, 2014). "Long noncoding RNA (lncRNA) within mRNA sequences of Alzheimer's disease genes, namely, APP, APOE, PSEN1, and PSEN2, has been analyzed using fractal dimension (FD) computation and correlation analysis." (PMID 23662159, 2013). "The long noncoding RNAs (lncRNAs) within the mRNA sequences in Alzheimer's disease genes, namely, APP, APOE, PSEN1, and PSEN2, have been analyzed in terms of fractal dimension computation and correlation analysis." (PMID 23662159, 2013).